LDHA (lactate dehydrogenase A)
Diseases named in the same sentence as LDHA in open-access papers (continued):
Sharing a sentence is not in itself a finding about the gene and the disease.
colon carcinoma (40 papers, 2011 to 2025). "We also found that C. tropicalis significantly enhanced the expression of enzymes associated with glycolysis, GLUT1, HK2, PKM2 and LDHA in colon tumor tissues, which was attenuated by TEPP-46 treatment." (PMID 36348389, 2022). "Recently, direct targeting of LDHA by miR-34a was shown to re-sensitize colon cancer cells to 5-fluorouracil, and miR-34a was found to be silenced by the aberrant CpG methylation of its promoter in various cancers." (PMID 39930542, 2025). "Accordingly, concentration of Fe2+ and MDA (%) was also rescued after LDHA was overexpressed in colon cancer cell lines." (PMID 36923931, 2023). "Oxidative stress, COX-2, LDHA and hyperglycemia are interlinked contributing pathways in the etiology, progression and metastasis of colon cancer." (PMID 37895863, 2023). "In colon cancer, the inhibition of LDHA significantly reduced the extracellular level of lactate which leads to an inhibition of TAM-derived VEGF and tube formation." (PMID 36319992, 2022). "Matrine has been found in studies to drastically suppress the expression of HIF-1α and its downstream regulatory targets of glucose metabolism GLUT1, HK2 and LDHA in colon cancer HCT116 and SW620 cells, reversing the Warburg Effect." (PMID 36339566, 2022). "Recently, AK6 was proposed to be a potent modulator of metabolic reprogramming by regulating lactate dehydrogenase A (LDHA) activity in colon cancer stem cells." (PMID 33471801, 2021). "On the basis of detection result, the ECAR, glucose intake, lactate production, ATP/ADP ratio, and GLUT1 and LDHA expression of LoVo colon cancer were apparently diminished by knocking down c-MYC." (PMID 34921134, 2021). "In an acidic tumor microenvironment, fructose-bisphosphate aldolase A (ALDOA), pyruvate kinase muscle isozyme M2 (PKM2,) and lactate dehydrogenase A (LDHA) are overexpressed in colon cancer, resulting in high acidity of the intracellular environment." (PMID 33401375, 2021). "Another recent study reported that LDHA is a direct target of miR-34a, and the inhibition of LDHA by miR-34a promotes the re-sensitization of 5-fluorouracil-resistant colon cancer cells." (PMID 32038983, 2020). "In advanced colon cancer, miR‐34a was significantly down‐regulated in 5‐fluorouracil‐resistant cancer tissues, while the expression of LDHA was abnormally increased." (PMID 30403008, 2018). "It has been shown that the maintenance of low pyruvate level in colon cancer cells caused by the silencing of LDHB and the up-regulation of LDHA resulted in avoidance from cell death." (PMID 22363243, 2011). "Furthermore, molecular validation using Western blotting revealed elevated expression of colon cancer-associated markers, including HK2 and LDHA, in tumor-bearing liver tissues." (PMID 40647563, 2025).
colon carcinoma (continued). "Hydroxyisoxazole-4-carboxylic acid (HICA) and 1-(phenylseleno)-4-(trifluoromethyl) benzene (PSTMB) also act as pyruvate competitors, inhibiting LDHA and disrupting mitochondrial membrane integrity, thereby inhibiting the proliferation of human colon cancer cells." (PMID 39683818, 2024). "IGF2BP1 facilitates the glycolysis of colon cancer by binding and stabilising the LDHA, which could promote the lactic acid accumulation and acidic TME production." (PMID 36747239, 2023). "Moreover, TMRE analysis and TEM analysis demonstrated that overexpression of LDHA significantly inhibits ferroptosis of colon cancer cells." (PMID 36923931, 2023). "Additionally, targeting the aberrant glucose metabolism through LDHA inhibitors can restrict cholesterol-induced colon cancer cell proliferation." (PMID 37705114, 2023). "Moreover, in colon cancer an increased activity of LDHA induces overproduction of lactate and enhances the secretion of metalloproteinases, which can be reversed by LDH inhibitors." (PMID 36319992, 2022). "Consistent with the results of the current study, IGF2BP1 could bind with LDHA 3′-UTR, thus resulting in enhanced LDHA mRNA stability and increased glycolysis in colon cancer cells." (PMID 35918761, 2022). "Thus, in colon cancer cells, H2S-induced stimulation of the catalytic activity of LDHA leads to the stimulation of mitochondrial electron transport." (PMID 34884491, 2021). "Similarly, GEPIA database also revealed that HIF1A expression positively correlated with HK2 and LDHA in colon cancer, rectal cancer and CRC, respectively." (PMID 33218358, 2020). "However, the ATAT1 activity is required for microtubule organization, it is specifically upregulated in colon cancer tissue and LDHA has an aberrantly high expression in multiple cancers." (PMID 31540229, 2019). "LDHA is regarded as a potential prognostic biomarker, and over-expression of LDHA is closely correlated with intrahepatic metastasis, early recurrence and worse prognosis in colon cancer." (PMID 28193910, 2017). "METTL3/LDHA axis-induced glucose metabolism may be a potential therapeutic target for CRC cells to overcome 5-FU resistance, which was demonstrated to be associated with overexpression of GLUT1 in colon cancer cells." (PMID 36778600, 2022). "These compounds were evaluated for their antioxidant activity, inhibition of PDK-1 and LDHA, as well as their antiproliferative effects against HCT-116 and LoVo colon carcinoma cell lines." (PMID 40573199, 2025). "Overexpression of LDHA inhibits RSL3-induced ferroptosis through evaluating cell viability and cell death rates on colon cancer cell line CACO2." (PMID 36923931, 2023). "The overexpression of GGH in colon cancer-derived cell lines (SW48 and SW480) inhibited PKM, GLUT1, and LDHA expression and decreased the extracellular lactate content and intracellular ATP level." (PMID 36569910, 2022). "It has also been shown that the treatment of HCT116 colon cancer cells with low concentrations of GYY4137 increases mitochondrial function and glycolysis by persulfidating the Cys-163 of the lactate dehydrogenase A (LDHA) resulting in its stimulation." (PMID 33390834, 2021). "Lactate dehydrogenase A (LDHA), a target of miR-34a, is significantly elevated in 5-FU resistant colon carcinoma cells." (PMID 32503256, 2020).
colon carcinoma (continued). "In HT29 colon cancer cells, all three targets (GLUT1, LDHA and MCT4) were activated, and increased glucose uptake and lactate release by stimulation with PDGF was detectable." (PMID 27626684, 2016). "Primary human colon cancers demonstrated a significant activation of GLUT1, LDHA, and MCT4 gene expression, which supports the importance of glycolysis in colon cancer, particularly at late stages." (PMID 27626684, 2016). "In primary colon cancer, a constitutively increased mRNA expression of the glycolysis markers GLUT1, LDHA, and MCT4 was observed." (PMID 27626684, 2016). "In colon cancer cell lines, overexpression of the mitochondrial glutamate transporter SLC25A18 reduced glucose uptake and downregulated β-catenin, Lactate Dehydrogenase A (LDHA), and Pyruvate Kinase M2 (PKM2), while its deletion had the opposite effect." (PMID 40917745, 2025). "We found that POU2F1 transcripts were positively correlated with hexokinase 2 (HK2), 6-phosphofructo-2-kinase/fructose-2,6-biphosphatase 2 (PFKFB2), ALDOA, pyruvate kinase M1/2 (PKM), lactate dehydrogenase A (LDHA), G6PD, and ribose 5-phosphate isomerase A (RPIA) levels in the colon cancer tissues." (PMID 34997215, 2022). "Moreover, in vitro and in vivo investigations on colon cancer showed that wogonin inhibited HIF-1α, HK2, PDK1, and LDHA expression." (PMID 36339566, 2022). "Matrine could drastically decreased HIF-1α and its downstream regulatory targets of glucose metabolism such as GLUT1, HK2 and LDHA in HCT116 and SW620 colon cancer cells, thus reversing the Warburg Effect." (PMID 36339566, 2022). "Although a study demonstrated that the inhibition of LDHA by microRNA-34a recovered the resistance to 5FU in colon cancer, no previous study has reported the effects of genetic or pharmacological LDHA inhibitors on chemoresistance." (PMID 34065602, 2021). "Analysis using the GEPIA dataset indicates that the YAP1 levels were positively correlated with TEAD1 in colon cancer, rectal cancer and CRC, and surprisingly, the YAP1 and TEAD1 levels were both positively correlated with HIF1A or LDHA." (PMID 33218358, 2020). "In HT29 human colon cancer cells, PSTMB dose-dependently inhibited the viability of the cells and activity of LDHA, without affecting the expression of LDHA." (PMID 30850682, 2019).
bladder cancer (36 papers, 2017 to 2026). "Analysis of human bladder cancer specimens reveals that HK2 expression positively correlates with MYC and LDHA levels and associates with worse patient survival, particularly in patients with hyperglycemia." (PMID 41951587, 2026). "It is interesting to highlight the previous work showing that STAT3 transcriptionally upregulates LDHA in thyroid and bladder cancer cells." (PMID 38443336, 2024). "Inhibition of LDHA reduces the proliferation of many cancer cells, such as those in kidney, breast, and bladder cancers." (PMID 36894874, 2023). "For example, has-circRNA-403658, a hypoxia-responsive circRNA in bladder cancer, promotes LDHA-mediated aerobic glycolysis and growth in bladder cancer cell." (PMID 35915091, 2022). "LDHA has been also reported to be targeted by different miRNAs in various cancers, including osteosarcoma and bladder cancer." (PMID 36033372, 2022). "STAT3 has been shown to affect cellular metabolism, through increased glucose consumption, and lactate production in bladder cancer, through increased transcription of LDHA, ENO2, HK2, and IGFBP3." (PMID 36230984, 2022). "PLCε was found to be upregulated in bladder cancer and caused the stimulation of STAT3 phosphorylation, which regulates the transcription of LDHA and, as a result, affects glucose consumption and lactate production." (PMID 36230984, 2022). "Oncological research has reported that HIF-1α upregulation significantly promoted LDHA expression in bladder cancer cells." (PMID 35090526, 2022). "Hypoxia-induced circular RNA has_circRNA_403,658 promotes bladder cancer cell growth through activation of LDHA." (PMID 34869590, 2021). "Has-circRNA-403658 silencing inhibits the LDHA-mediated aerobic glycolysis, thereby the growth and proliferation of bladder cancer cells." (PMID 32513983, 2020). "Recent studies reported that LDHA can promote the progression of renal cell carcinoma and bladder cancer by promoting EMT." (PMID 31921691, 2019). "Overexpression of LDHA relieved the growth inhibition and cell apoptosis enhancement by miR-204-3p in bladder cancer cells." (PMID 31850191, 2019). "LDHA expression was evaluated in 30 bladder cancer (BC) and 30 matched normal bladder (Normal) samples by qRT-PCR." (PMID 28978061, 2017). "Up-regulation of LDHA was confirmed by Western blot analysis of four bladder cancer and four matched normal bladder samples (right)." (PMID 28978061, 2017). "MiR-200c directly targets LDHA to suppress cell glycolysis, proliferation, and invasion in bladder cancer." (PMID 28978061, 2017). "We also demonstrated that miR-200c targets LDHA and inhibits cell proliferation, invasion, and glycolysis in bladder cancer cells." (PMID 28978061, 2017). "Hexokinase II, PFK, PDH, and LDHA protein expression are increased in invasive bladder cancer cells compared with UROtsa cells." (PMID 28766915, 2017). "We demonstrate that LDHA is up-regulated in bladder cancer cells and promotes proliferation, invasion, and glycolysis." (PMID 28978061, 2017). "Indeed, LDHA overexpression has been documented across various malignancies, including breast, colorectal, gastric, lung, liver, brain, and bladder cancers, positioning LDHA as an important therapeutic target and prognostic biomarker." (PMID 40733189, 2025). "LDHA was increased under hypoxia and promoted the development of bladder cancer." (PMID 38990159, 2024). "Furthermore, to validate the biological functions of histone lactylation in bladder cancer, we eliminated endogenous LDHA and LDHB to reduce global lactylation and H3K18 lactylation levels and replenished sodium lactate for rescue experiments." (PMID 37684641, 2023). "Furthermore, STAT3 up-regulates LDHA expression to promote the proliferation of urinary bladder cancer cells." (PMID 34326684, 2021). "Overexpression of CASC8 through interacting with FGFR1 and inhibiting FGFR1-mediated LDHA phosphorylation could suppress glycolysis in bladder cancer cell." (PMID 33123468, 2020).
bladder cancer (continued). "We performed luciferase reporter assays in T24 bladder cancer cells to determine whether LDHA was a direct target of miR-200c." (PMID 28978061, 2017). "We investigated whether miR-200c inhibited glycolysis, cell proliferation, or invasion in bladder cancer cells by targeting LDHA." (PMID 28978061, 2017). "We found that LDHA was up-regulated in bladder cancer tissue (left)." (PMID 28978061, 2017). "We found that miR-200c expression was inversely correlated with LDHA expression in bladder cancer." (PMID 28978061, 2017). "We investigated LDHA expression and function in bladder cancer." (PMID 28978061, 2017). "We found that LDHA is up-regulated in bladder cancer and that it acts as an oncogene." (PMID 28978061, 2017). "Thus, miR-200c suppresses LDHA-induced glycolysis, cell proliferation, and invasion in bladder cancer." (PMID 28978061, 2017). "Thus, LDHA is up-regulated in bladder cancer and it promotes cell proliferation and invasion." (PMID 28978061, 2017). "Therefore, LDHA is a direct target of miR-200c in bladder cancer." (PMID 28978061, 2017). "Inhibition of LDHA may be an effective therapeutic strategy in bladder cancer." (PMID 28978061, 2017). "Additionally, we found that microRNA (miR)-200c directly targets LDHA in bladder cancer cells." (PMID 28978061, 2017). "Thus, targeting LDHA through miR-200c is a potential therapeutic strategy in bladder cancer." (PMID 28978061, 2017). "In contrast, miR-489-3p regulates LDHA and PKM2 in pancreatic cancer29DLX1 in prostate cancer30SIX1 in melanoma31and HDAC2 in bladder cancer to inhibit tumor growth." (PMID 40858914, 2025). "Our results demonstrated that the CXCL14/CCR7/STAT3 axis significantly promotes the glycolytic shift in bladder cancer cells by upregulating the expression of HK2 and LDHA, two key glycolytic enzymes." (PMID 40898244, 2025). "In this study, we investigated the effects of the aqueous extract of Cinnamon on human bladder carcinoma cell line 5637, especially on the gene expression of HSF1, ErbB2, and LDHA and the level of LDHA and HSF1 proteins and apoptosis." (PMID 35990198, 2022). "Hyperglycemia upregulates HK2 and promotes its nuclear localization in bladder cancer cells, where nuclear HK2 forms a complex with MYC to co-activate HK2 and LDHA transcription, thereby enhancing glycolysis, stemness, and tumor growth in hyperglycemic conditions." (PMID 41951587, 2026). "Thus, overexpression of genes related to glycolytic processes, such as GLUT1, GLUT3, HK2, LDHA, and PKM, is common in bladder cancer tissues and cells." (PMID 37258572, 2023). "Meanwhile, the cell viability of GEM-R bladder cancer cells induced by NXPH4 overexpression could be inhibited by 2-DG, BAY-876 (inhibitor for GLUT1), or oxamate (inhibitor of LDHA)." (PMID 35954445, 2022). "Accordingly, in invasive bladder cell lines and in muscle-invasive bladder cancer specimens, it was found a correlation between EMT markers and high levels of lactate dehydrogenase A (LDHA) expression, the enzyme that mainly converts pyruvate into lactate in the end of glycolysis." (PMID 34150624, 2021). "Moreover, Western blot analysis showed that Vitamin K2 stepwise elevated the expression of some glycolytic proteins or enzymes, such as GLUT-1, Hexokinase II (HK2), PFKFB2, LDHA and PDHK1, in bladder cancer T24 and EJ cells." (PMID 32382009, 2020). "MiR-200c was down-regulated in bladder cancer tissue, and a negative correlation was observed between LDHA expression and miR-200c." (PMID 28978061, 2017).